OR10T2 (olfactory receptor family 10 subfamily T member 2)
Description:
Odorant receptor.
Synonyms: OR1-3
Tractability: Antibody: UniProt places it where antibodies can reach, with medium confidence; UniProt predicts a signal peptide or a membrane-spanning region; its Gene Ontology location is reachable by antibodies, with medium confidence.
Gene: Protein-coding gene on chromosome 1 (158,398,522 to 158,399,466, reverse strand). Ensembl gene ENSG00000186306.
Subcellular location: Cell membrane
Pathways (Reactome):
Sensory Perception: Expression and translocation of olfactory receptors
Gene Ontology:
Molecular function: odorant binding; olfactory receptor activity; G protein-coupled receptor activity
Biological process: detection of chemical stimulus involved in sensory perception of smell; G protein-coupled receptor signaling pathway
Cellular component: membrane; plasma membrane
Genetic constraint (gnomAD): Missense variants: 408 observed, 386.24 expected, observed/expected ratio (o/e) 1.06, 90% interval 0.97 to 1.15. Synonymous variants: 161 observed, 150.72 expected, observed/expected ratio (o/e) 1.07, 90% interval 0.94 to 1.22.
Homologues: Orthologues: chimpanzee OR10T2 (98% identical), rabbit OR10T2 (91% identical), pig OR10T2 (90% identical), dog OR10T2 (90% identical). Paralogues in human: OR10R2 (59% identical), OR10Z1 (53% identical), OR10K1 (52% identical), OR10J1 (51% identical), OR10J5 (51% identical), OR10K2 (50% identical), OR10J3 (48% identical), OR1L1 (44% identical), OR2A25 (44% identical), OR1E1 (43% identical), OR4B1 (43% identical), OR1E2 (42% identical), and 116 more.
Diseases named in the same sentence as OR10T2 in open-access papers:
OR10T2 is named in the same sentence as 1 disease in open-access papers, as found by Europe PMC text mining. Sharing a sentence is not in itself a finding about the gene and the disease. The quoted sentences say what the papers report.
cancer (1 paper, 2017). A tumor composed of atypical neoplastic, often pleomorphic cells that invade other tissues. "Further, five genes, ALMS1, TRAPPC9, CEP128, OR10T2, and CPVL, are among the SCLC genes but not in any of the common cancer gene lists, yet these genes were mutated in M9." (PMID 29050228, 2017).